CXCR4 (C-X-C motif chemokine receptor 4)
Diseases named in the same sentence as CXCR4 in open-access papers (continued):
Sharing a sentence is not in itself a finding about the gene and the disease.
tumor (continued). "In the endosteal niche, tumour cells are thought to be held in a quiescent state through CXCR4/CXCL12 interactions using similar mechanisms to those used by osteoblasts to maintain quiescence of HSCs." (PMID 29760166, 2018). "With regard to the second direction of incorporation of CXCR4 antagonist into ICIs therapeutic protocols, several preclinical works have indicated that CXCL12/CXCR4 interactions in the tumor microenvironment mediate immune evasion and resistance to ICIs." (PMID 30257500, 2018). "Following, we analyzed the fraction of CXCR4+ cancer cells (CXCR4+ CCF) remaining in tumor tissue, along time, after a single 100 μg T22‐GFP‐H6‐FdU dose, as compared to free oligo‐FdU, using the SC CXCR4+ SW1417 CRC model in NOD/SCID mice." (PMID 30190334, 2018). "Our current study also showed that silencing of CXCR4 expression reduced BTIC tumor sphere formation and xenograft growth of tumor." (PMID 30486409, 2018). "CXCR4 is a cell surface receptor yet various studies show that it can be expressed at different sites with different tumour behaviour." (PMID 29887884, 2018). "The expression of CXCR4 in the nuclear, cytoplasmic, and the membrane staining of tumour cells all have a different prognosis." (PMID 29887884, 2018). "In contrast, the CXCR4+ CCF in tumor tissue after free oligo‐FdU therapy was maintained over time, remaining similar at 24, 48, or 72 h after treatment as before therapy." (PMID 30190334, 2018). "Analysis showed that 67% primary tumours of the stomach with peritoneal metastasis were positive for CXCR4 expression, in comparison to 25% with another distant metastasis were positive." (PMID 29867026, 2018). "Tumor-derived TGF-β then induces CXCR4 on TAMs, stimulating them to migrate toward CXCL12-expressing perivascular fibroblasts." (PMID 29719241, 2018). "In the context of cancer, CXCR4 expression is found on tumor cells, where it promotes tumor cell growth, migration, and invasiveness." (PMID 30319622, 2018). "CXCR4 is not only expressed by cancer cells themselves, but also by tumor-infiltrating immune cells." (PMID 30191351, 2018). "In contrast, the CXCR4+ CCF in tumor tissue after an equimolecular dose of free oligo‐FdU remained similar to its basal level along time." (PMID 30190334, 2018). "The progression of a tumour during carcinogenesis can be related to its intratumoural hypoxia by upregulating the CXCR4 expression in the tumour cells." (PMID 29887884, 2018). "The CXCR4/SDF-1 axis plays a major role in the BM localization of MM tumor cells and in the regulation of MM cells trafficking." (PMID 29844860, 2018). "The invasive carcinomas of no special type (NST) displayed inter- and intratumoral heterogeneity of CXCR4 expression in the tumor cell-infiltrating immune cells and within the tumor cells." (PMID 30191351, 2018). "Monocytic MDSCs, that include macrophages at different maturation stages, express CCR2, CXCR2 and CXCR4, and can reach the tumor via their specific ligands CCL2, CXCL5 and CXCL12 respectively." (PMID 30319638, 2018). "Aside from enhanced cDC isolation yield, CXCR4 expression within total cDCs remained similar between tumor and naïve mice, with 76.6% of splenic cDCs from tumor mice expressing CXCR4." (PMID 30489627, 2018). "Another pathway recently implicated in pericyte recruitment is stromal-derived factor 1-a (SDF-1a)/CXCR4 axis which activation promotes pericyte migration in vitro and in vivo, during tumor angiogenesis." (PMID 29519245, 2018). "The aim of this review is to merge the knowledge on the role of SDF-1/CXCR4 in tumor biology, radiotherapy and immunotherapy of cancer and in combinatorial approaches." (PMID 30622535, 2018). "It was shown, analyzing more than 600 PCa specimens that the CXCR4 protein expression increased with tumor progression." (PMID 29396484, 2018). "As is observed with other cancers, CXCR4 expression correlates with “cancer stem-cell” properties which include a propensity for tumor initiation and metastasis." (PMID 29930538, 2018).
tumor (continued). "In this study, we compared the effects of CXCR4 antagonists on apoptosis induction in hematopoietic cells and in tumor cells." (PMID 29682200, 2018). "Known mechanisms are Calcium release, ERK1/2 phosphorylation, IP3/Akt activation, and MAP signaling activation are all downstream of CXCR4 activation and lead to greater invasiveness and to the proliferation of diverse tumor cells." (PMID 29515781, 2018). "CXCR4 inhibition appeared promising in in vitro MM models by enhancing the sensitivity of tumor cells to chemotherapy or other targeted therapies." (PMID 29844860, 2018). "The immunohistochemistry (IHC) was performed to evaluate the associations between the expression level of CD164 and clinical‐pathological features of patients, and IHC was used to analyze the relationship between CD164 and CXCR4 in tumor tissues." (PMID 30022623, 2018). "The expression levels of SDF1/CXCR4 were all higher in F and P tumor cells than in normal liver cells and tissues in vitro and in vivo." (PMID 29783989, 2018). "Within the tumor microenvironment, the major CXCR4-expressing cells are B-lymphocytes and plasmacytoid dendritic cells, both potentially contributing to an immunosuppressive site permissive for tumor progression." (PMID 30191351, 2018). "The SDF-1/CXCR4 axis plays pivotal roles in various aspects of tumor biology, and in particular in the stress response of tumors to ionizing radiation." (PMID 30622535, 2018). "CXCR4, cooperate with chemokine receptor (CCR1 and/or CCR2) to promote metastasis-associated macrophage (MAM) accumulation and thereby metastatic tumor growth." (PMID 30190788, 2018). "Tumoral CXCR4 expression has also been detected on circulating tumor cells as well as in liver, lung, and nodal metastases." (PMID 30420855, 2018). "The interaction of CXCL12 and CXCR4 has been addressed as engaging in the tumour progression of various cancers, including CRC." (PMID 29887884, 2018). "The SDF-1α/CXCR4 signaling pathway involved not only in tumor cell proliferation, migration and angiogenesis, but also in immune surveillance of tissues." (PMID 30349420, 2018). "Recent studies have shown that CXCR4 has different expression patterns of tumour cells, which suggests a different biological behaviour by cancer." (PMID 29887884, 2018). "The tumor model used in this study was the B16 melanoma cell line which perhaps also suggests that the role of CXCR4 in osteolysis is dependent on the context of other factors secreted by tumor cells." (PMID 29930538, 2018). "Some studies have suggested that both CXCL12 and CXCR4 contributed significantly during angiogenesis and hematopoietic stem cell mobilization, while others have suggested its major contribution during tumour development." (PMID 30060445, 2018). "To determine the feasibility of using splenic cDCs for adoptive transfer experiments and to explore potential differences between cDCs of naïve and FLT-3 ligand-secreting tumor mice, we assessed CXCR4 expression and the maturation status of splenic cDCs." (PMID 30489627, 2018). "Before treatment, both groups showed a similar CXCR4+ CCF in tumor tissue; however, after T22‐GFP‐H6‐FdU treatment, the CXCR4+ CCF was reduced at 24 h and reached its valley at 48 h." (PMID 30190334, 2018). "High levels of CXCL12 in tumour tissue will invite CXCR4-positive inflammatory, endothelial, and stromal cells into the tumour." (PMID 29887884, 2018). "The present article, therefore, aims to give an overview about the plethora of functions of SDF-1/CXCR4 signaling in tumor biology and immune responses in the context of combined radiotherapy and immunotherapy." (PMID 30622535, 2018). "To estimate the potential impact of deregulated CXCR4 activity in tumor tissue, we investigated the recently described alternative DAMP ligand, ubiquitin." (PMID 29721166, 2018). "CXCR4 has also been shown to be expressed in many hematologic cancers as well as solid tumors and it was suggested to have a role in tumor survival." (PMID 29844860, 2018).
tumor (continued). "In vivo, treatment with the CXCR4 antagonist AMD3100 significantly reduced SDF-1+CD206+ macrophage accumulation around tumour vessels after radiotherapy, with increased iNOS+ M1 macrophage and non-differentiated SDF-1+ monocyte populations." (PMID 30504836, 2018). "The knockdown of miR‐9 or overexpression of CXCR4 in HNSCC cell lines had similar consequences on tumour cell behaviour." (PMID 29959873, 2018). "Remarkably, recent data also link CXCR4 blockade with antitumor immunity in the tumor immune microenvironment suggesting SDF-1/CXCR4-targeting as a therapeutic tool to interfere with the immune system." (PMID 30622535, 2018). "CXCR4 staining of the tumor microvessels was even detected in 50% of the HCC samples and in 56% of the CCC samples." (PMID 29282035, 2017). "The PepR-NIR750 CXCR4 tracer will allow to visualize in vivo the CXCR4 modulating drugs on tumor microenvironment through labeling of CXCR4 positive T and immunoregulatory cells." (PMID 28566721, 2017). "Cancer cell CXCR4 expression has been shown to promote tumor progression, suggesting that CXCR4 plays a critical role in the tumorigenesis of CRC." (PMID 29117108, 2017). "Recent studies showed that CXCR4 play an important role in promoting EMT process of tumor cells, including GBM." (PMID 29113309, 2017). "We show also that bevacizumab-mediated inhibition of tumor growth can be amplified by the simultaneous blockade of the CXCR4 and VEGFR." (PMID 28057017, 2017). "Expression of CXCR4 mRNA expression in tumor tissue was demonstrated quantitatively and semiquantitatively via mRNA analysis." (PMID 29221153, 2017). "SDF-1α–CXCR4 signaling has been shown to play a key role in tumor growth, invasion, and angiogenesis." (PMID 28415580, 2017). "Consistent with the in vitro assay, mifepristone was able to down-regulate the CXCR4 expression of tumor tissue by immunohistochemical analysis, when compared with the untreated and SDF-1-treated mice." (PMID 28938623, 2017). "To date, it has been well-documented that the interaction between chemokine receptor 4 (CXCR4) and its ligand, stromal cell derived factor-1 (SDF-1, also termed as CXCL12), is closely associated with tumor cells adhesion, invasion and migration." (PMID 28793338, 2017). "CXCR4 is over-expressed in more than 20 human tumor types, promoting tumor growth and progression, tumor invasiveness and metastasis." (PMID 29228566, 2017). "The current study used the well-characterized tumor cell implantation (TCI)-induced cancer pain rat model to investigate the neuronal mechanism of CXCR4 signaling pathway in the pathophysiology of CIBP." (PMID 28638088, 2017). "In these drug resistant tumor cells the CXCR4 inhibitor plerixafor (AMD3100) exhibits significant anti-tumorigenic effects." (PMID 28402937, 2017). "An interplay exists between CSCs, differentiated GBM cells, and the microenvironment, mainly through secreted chemokines causing recruitment of fibroblasts, endothelial, mesenchymal, and inflammatory cells to the tumor, via CXCR4." (PMID 28057017, 2017). "Tissue decolorization and 3D reconstitution successfully emphasized remarkable expansion of Cxcl12/Cxcr4 expressing cells within antral tumor." (PMID 29340033, 2017). "Collection of circulating tumor cells (CTCs) permits evaluation of biomarkers such as CXCR4 expression in patients with SCLC, as CTCs are present in high numbers in the peripheral blood of patients with SCLC." (PMID 28299514, 2017). "Patient stratification should be mandatory by expression (e.g. PD-L1, CXCR4, COX2) or mutational (EGFRm) analysis in tumor biopsies." (PMID 28402937, 2017). "Their product NOX-A12 functions as a CXCL12 inhibitor and enabled the release of CXCL12 from the surface of tumor stromal cells and blocked its interaction with cell surface receptors CXCR4 and CXCR7." (PMID 28620386, 2017).
tumor (continued). "The atypical chemokine receptor 3 (ACKR3), which does not couple to G-proteins and does not mediate cell migration, acts as a scavenger for CXCL11 and CXCL12, interfering with the tumor homing CXCL12/CXCR4 axis." (PMID 29156704, 2017). "To present, various antagonists targeting CXCR4 have been developed for uses in a variety of preclinical tumor models." (PMID 29263923, 2017). "Inflammatory chemokine CXCL12 of enriched organs forms a concentration gradient and attracts CXCR4 positive tumour cells to homing by directed movement." (PMID 28403883, 2017). "Optimum cutoff values were H-score ≥ 210 for CXCR4+ tumor, ≥7% CTCs with CXCR4 expression (CXCR4+ CTCs), and ≥6 CTCs/7.5 mL blood." (PMID 28299514, 2017). "The Rluc activity of MDAMB23/Rluc was shown in a xenograft mice model, and the in vivo results showed that the tumor recruits more CXCR4-overexpressing MSCs than native MSCs." (PMID 28740515, 2017). "Subsequent work reported that cell surface expression of CD133/CXCR4 marked a more restricted population of metastatic, therapy-resistant tumor-initiating cells." (PMID 28855593, 2017). "The CXCR4/CXCL12 axis is used by tumor cells which secrete platelet-derived growth factor (PDGF) that in turn activates endothelial cells to secrete CXCL12 leading to a chemotaxis gradient." (PMID 28785589, 2017). "The aim of this study is to investigate various methods for quantification of CXCR4 availability using N-[11C]methyl-AMD3465 PET in immune-competent tumor-bearing rats." (PMID 27896627, 2017). "Tumor uptake of [64Cu]NOTA-pentixather was significantly higher than tracer accumulation in all other organs (13.1 ± 1.5% ID/g), underlining its excellent CXCR4 targeting efficiency." (PMID 29527563, 2017). "Here we show that Peptide R-NIR750 specifically binds to CXCR4 overexpressing tumor cells in vitro and in vivo and discriminates the effect of Peptide R treatment on the development of lung metastases through fluorescence molecular tomography." (PMID 28566721, 2017). "This indicates that effective tumor detection would still be possible, even when a CXCR4 positive stromal cell infiltrates are present." (PMID 28549419, 2017). "Several stem cell markers including CXCR4 and CD117 were associated with increased angiogenesis and escape from tumor hypoxia." (PMID 28690641, 2017). "QRHX treatment blocked the response of macrophages to tumor signals by suppressing CXCL12/CXCR4/JAK2/STAT3 expression and induced a remarkable decrease of the recruitment of M2 macrophages, suggesting the attenuation of M2 subtype cells function by QRHX." (PMID 28630636, 2017). "The CXCL12/CXCR4 axis is related to mediating tumour cell invasion and proliferation and plays an important role in tumour angiogenesis, progression and metastasis." (PMID 28386296, 2017). "Between the SSTR5 or CXCR4 positivity of tumor microvessels and all other pathological or clinical parameters recorded no further significant association was found." (PMID 29282035, 2017). "There were no statistical differences between treatment arms for baseline tumor CXCR4 expression, CXCR4 expression in CTCs, and CTC counts." (PMID 28299514, 2017). "Tumor-associated hypoxia is known to upregulate hypoxia inducible factor 1-α (HIF1-α), transcribe stromal cell-derived factor 1α (SDF-1α), and promote secretion of proangiogenic factors to recruit CXCR4+ bone marrow-derived cells (BMDCs) in the tumor milieu." (PMID 29062041, 2017). "AMD3100 is a small molecule antagonist of CXCR4 that has been shown to promote the apoptosis of tumor cells and the local T-cell mediated immune responses." (PMID 28196146, 2017). "These optimum cutoff values were: H-score ≥ 210 for CXCR4+ tumor tissue, CTCs ≥6/7.5 mL blood, and CXCR4+ CTCs ≥7%, and were evaluated by treatment and visit or endpoint." (PMID 28299514, 2017).
tumor (continued). "In the metastasis-containing lymph node samples, SSTR2 and CXCR4 were strongly expressed in germinal centers of (activated) lymph follicles in close proximity to the tumor cells." (PMID 29282035, 2017). "The mean percentage of CXCR4 positive cells was 60.91 ± 0.06, 60.27 ± 0.05 and 60.60 ± 0.05 for the whole tumor tissue, central part and peripheral part of the tumors indicating no relevant difference between those three tumor regions." (PMID 29221153, 2017). "Anti-PD-1 mAb administration did not significantly delay tumor growth when combined with sorafenib alone, even if the combination of an anti-PD-1 with sorafenib and AMD3100, an anti-CXCR-4 molecule, notably restrained tumor growth and metastasis." (PMID 28420805, 2017). "In vitro and in vivo studies also have shown a correlation between tumor metastasis and alterations in CXCR4/CXCL12 signaling in PDAC." (PMID 28356064, 2017). "The data showed that CXCL12 treatment or CXCL12 treatment combined with CXCR4 overexpression reduced the anti-tumor effect of SGC-7901 and MKN-45 gastric cells to regorafenib." (PMID 28489887, 2017). "CXCR4 is overexpressed in more than twenty types of human cancer, and the CXCL12-CXCR4 interaction in the tumor microenvironment controls tumor cell survival and resistance to chemotherapy." (PMID 28945785, 2017). "Fourth, the roles of CXCR4 antagonists in suppressing tumor growth, invasion, and metastasis are similar both in vitro and in vivo." (PMID 28544785, 2017). "In the majority of studies, CXCR4 expression was higher in tumors than in normal liver tissues and was correlated with tumor aggressiveness and reduced patient survival." (PMID 29282035, 2017). "Further evidences suggest a critical role of the CXCL12/CXCR4 axis in tumor initiation, metastatic colonization and resistance to chemotherapy." (PMID 28176874, 2017). "An oncolytic virus armed with a CXCR4 antagonist effectively inhibited the development of spontaneous metastasis and increased overall tumor-free survival." (PMID 28415580, 2017). "The inhibition of CXCR4 led to diversified tumor-elimination effects by restoring and enabling the rapid intratumoral accumulation of cytotoxic CD8+ T cells." (PMID 28753978, 2017). "Similar like BAG3, CXCR4 mRNA was significantly upregulated in breast cancer tumor specimens compared with corresponding non-tumor tissues." (PMID 28703799, 2017). "The role of CXCR4 signaling in regulating key aspects of tumor progression such as angiogenesis has prompted the development of CXCR4 antagonists such as ADM3100, the first identified potent and selective CXCR4 antagonist." (PMID 29240722, 2017). "Several studies have shown that some tumor cells, in addition to expressing CXCR4, can secrete CXCL12 and so activate an autocrine loop promoting growth and metastasis." (PMID 28055968, 2017). "A higher CXCR4-expression enables tumour cells to migrate towards SDF-1 and enhances proliferation and tumour dissemination." (PMID 28542132, 2017). "The main functions of the top genes in OSPC2 network were associated to sensitization to chemotherapy (CXCR4, ANKRD1, CYR61, EDN1, ATP1B1, ARHGEF1, RTF1), and tumor suppression (FGFR3, BCL11B)." (PMID 28482906, 2017). "Due to the importance of CXCR4 in tumor cells invasion and migration, it is highly desirable to develop a new CXCR4 antagonist with high efficacy and low toxicity for tumor therapy." (PMID 28793338, 2017). "Mouse models suggest that CXCR4 inhibitors like Plerixafor can reduce tumor metastasis and primary tumor growth." (PMID 37133296, 2017). "Since, induced FoxP3 are downregulated for CCR7 and CD62L as well as upregulated for memory or effector-type trafficking receptors such as CCR4, CCR5, CCR8, CCR10, and/or CXCR4, they can migrate into the tumor via the tumor-draining lymph nodes." (PMID 29450136, 2017). "The increased expression of CXCR4 in this population suggests that these cells constitute a relatively invasive population of tumor cells." (PMID 28486750, 2017).